CDK2 (cyclin dependent kinase 2)
Diseases named in the same sentence as CDK2 in open-access papers (continued):
Sharing a sentence is not in itself a finding about the gene and the disease.
lung carcinoma (continued). "CDK2, an important regulator of cell cycle, was consistently found to be overexpressed in human cancers, including lung cancer." (PMID 32635498, 2020). "As was previously shown by proteomic analysis of lung carcinoma cells, the knockdown of YTHDF1 led to activation of cell cycle inhibitor p27Kip1 and suppression of cell cycle activator genes encoding CDK2, CDK4 and cyclin D1." (PMID 33317545, 2020). "It has been reported that LATS2 inhibits the growth of lung cancer cells by downregulating the cyclin E/CDK2 kinase activity." (PMID 32892482, 2020). "We also observed that p21 directly interacts with CDK2 or PCNA, and the interaction between p21/CDK2 or p21/PCNA following parkin siRNA treatment was increased in A549 lung cancer cell lines." (PMID 31112565, 2019). "Pemetrexed reportedly induces S-phase arrest in A549 lung cancer cells by prolonging Akt activation, thereby sustaining activation of CDK2/cyclin A kinase." (PMID 28476017, 2017). "Overall, these findings demonstrate that PROS exerts antiangiogenic and apoptotic effects via inhibition of STAT3/VEGF/CDK2 axis signaling as a potent anticancer agent for lung cancer treatment." (PMID 29254203, 2017). "Overall, these findings suggest that PROS exerts antiangiogenic and apoptotic effects via inhibition of STAT3/ VEGF/ CDK2 axis signaling as a potent anticancer agent for lung cancer treatment." (PMID 29254203, 2017). "Phellinus linteus suppressed proliferation by the inhibition of cyclin-dependent kinases cdk2, 4 and 6, and induced apoptosis through the activation of caspase 3 in lung cancer cells and apoptosis of prostate cancer cells." (PMID 18362935, 2008). "Intriguingly, RNA-Seq of polyploid (4N) versus diploid (2N) lung cancer cells revealed specific clusters of expressed genes that could account for the survival and persistence of polyploid cancer cells, despite ongoing CDK2 antagonism." (PMID 40232858, 2025). "Intravital imaging of lung cancer fates after CDK2 inhibitor treatment." (PMID 40232858, 2025). "Targeting CDK2 has been explored as a potential therapeutic strategy for lung cancer treatment." (PMID 38905286, 2024). "For a better understanding of the bioactive mechanisms, four flavonoids (vitexin, kaempferol-3-O-rutinoside, luteolin, and isoorientin) were selected for molecular docking on hallmark protein targets in lung cancer as represented by γ-PI3K, EGFR, and CDK2 through in-silico studies." (PMID 38611505, 2024). "p57, a new member of the Kip/Cip family, is a broad‐acting CKI that is expressed in G1 and S phases of cells, inhibits DNA replication, and negatively regulates the cell cycle, its main substrate is CDK2, and it deletion or inactivation is common in human lung cancer cells." (PMID 39400513, 2024). "Notably, CCT6812749 and CYC06548 that each inhibit CDK2 activity also conferredstatistically-significant repression of tumor growth in mice bearing syngeneic or patient-derived xenografts (PDXs) of lung cancers." (PMID 38031910, 2023). "Likewise, baicalein caused cell cycle arrest in G1/S by inhibiting the Akt/mTOR pathway in H1299 and H1650 lung cancer cells, which decreased the expression of the proteins CDK2, CDK4, and cyclin E2." (PMID 37298837, 2023).
lung carcinoma (continued). "To further verify the role of NDUFA4 in the growth and metastasis of lung cancer cells, we detected the expression of cell-growth-related molecules including CDK2, CDK3, CDK4, and CDK6, as well as metastasis-related molecules including CXCR4, E-Cadherin, MMP2, MMP3, and MMP9, respectively." (PMID 28325285, 2017). "However, there are few studies on the mechanism of CDK2 in lung cancer." (PMID 34409029, 2021). "Cordycepin could cause cell cycle arrest via the inhibition of the cyclin B/CDK complex at G2/M transition in human bladder cancer cell lines or down-regulate cyclin E1, cyclin A and CDK2 to induce S phase arrest in human lung cancer cells and gallbladder cancer cells." (PMID 33172093, 2020). "In this study, the potential targets of Pinellia ternata highly overlap with lung cancer pathological genes, with FGFR4, CDK2, JAK2, KDR, PAK4, PTK2 and PDGFRA being the core." (PMID 42149884, 2026). "Dinaciclib has been previously shown to induce anaphase catastrophe in lung cancer cells through suppression of CDK1 and CDK2." (PMID 41080754, 2025). "We highlighted specific proteins, including AKR1B1, CDK2, DAPK1, PRDX1 and ALHD2 with potential as biomarkers for radon-related lung cancer." (PMID 40088196, 2025). "The objective of this study was to elucidate the biology of polyploid cells that arise after CDK2 inhibition in cultured normal HAEC and lung cancer cells as well as in PDX lung cancers." (PMID 40232858, 2025). "The proteins such as AKR1B1, CDK2, DAPK1, PRDX1 and ALDH2 show potential as biomarkers or therapeutic targets for radon-related lung cancer after further validation." (PMID 40088196, 2025). "CDK-2 inhibition has been considered in the treatment of highly aneuploid cancers, especially in KRAS-mutant lung cancer." (PMID 38184514, 2024). "It has recently been shown that CDK2 is targetable, and seliciclib (CYC202), a CDK2/7/9 inhibitor, induces apoptosis in lung cancer cells with supernumerary centrosomes through multipolar anaphase, which is termed anaphase catastrophe." (PMID 36621828, 2023). "We found increased mRNA levels of p21 and a significant decrease in cell cycle-promoting proteins such as CDK2, CDK4, cyclin E1, and cyclin D1, suggesting a possible tumor-suppressing role of LCK in liver and lung cancers." (PMID 36430477, 2022). "SU9516 is a cyclin-dependent kinase 2 inhibitor, exhibiting an inhibitory effect on the epithelial–mesenchymal transition (EMT) in A549 lung cancer cells." (PMID 38116825, 2022). "By inhibiting expression of cyclin A and CDK2, PES arrests the cell cycle in G0/G1 phase in lung cancer cells; however, PES induces G2/M phase arrest in nasopharyngeal carcinoma." (PMID 32110810, 2020). "Catechol attenuated the expression of CDK2 and CDK4 and their respective regulatory partners, cyclin E and cyclin D1 in a dose-dependent manner in KP2 and H460 lung cancer cells." (PMID 27167001, 2016). "To investigate the mechanism of cell cycle progression regulated by ATDC in lung cancer, we examined the effect of ATDC on cyclin A, cyclin D1, cyclin E, CDK2, CDK4, CDK6, p-Rb and c-Myc in lung cancer cell lines." (PMID 23776433, 2013). "We further showed that up-regulation of cyclin-dependent kinase 2 (CDK2) was critical for TLR9 signaling to stimulate the proliferation and cell cycle entry of human lung cancer cells." (PMID 23133627, 2012). "Independent of KRAS mutation status, substantial and statistically significant antineoplastic effects of CDK2 inhibition were observed in murine syngeneic and human PDX lung cancer models after CYC065 treatment, repressing primary and metastatic lung cancer growth in vivo." (PMID 40232858, 2025). "Within lung cancer—predominantly NSCLC (e.g., A549, H1299, H460, H2170)—coumarin scaffolds have been investigated as modulators of EMT/motility, topoisomerase I and CDK2 activity, Hsp90 chaperone function, and the PI3K/Akt/mTOR pathway, with coordinated effects on apoptosis and autophagy." (PMID 41226130, 2025).
lung carcinoma (continued). "In lung cancer, however, the antitumor activity of CDK2AP1 may act through affecting cell cycle regulators other than CDK2." (PMID 36105112, 2022). "In addition, dinaciclib was shown to trigger abnormal mitotic division (anaphase catastrophe) in lung cancer cells through, CDK1 and CDK2 suppression." (PMID 33777535, 2021). "Among several cell cycle regulatory proteins, the expression of CDK2 and PCNA was dramatically decreased in the lung tumor tissues of parkin KO mice compared with that in WT mice and parkin siRNA-transfected lung cancer cells." (PMID 31112565, 2019). "Interestingly, two additional drugs, SB525334 and SU9516, targeting TGFβR1 (TGFβ receptor 1) and CDK2 (cyclin dependent kinase 2), respectively, were identified in another high‐throughput screening showing EMT inhibitory activity in lung cancer cells." (PMID 28590039, 2017). "Taken together, these data indicate that CDK2 would be a good target for lung cancer treatment, and the measurement of CDK2SA could be useful for identifying patients who would receive the full benefit of CDK2 inhibitors." (PMID 25301183, 2014). "IRF1 is downregulated in lung cancer, IPF and PAH datasets, probably because it represses the expression of genes involved in anti-proliferative response, such as BIRC5/survivin, CCNB1, CCNE1, CDK1, CDK2 and CDK4 and in immune response, such as FOXP3, IL4, ANXA2 and TLR4." (PMID 31867044, 2019). "Our results, the upregulation expression of HSP90AA1 and CDK2 was related to the inhibited action of NSCLC cells, confirmed the important role of the core targets in lung cancer and may provide new ideas for the related research on guiding the clinical treatment of lung cancer." (PMID 35586682, 2022). "In addition, inhibition of CDK2, but not CDK1, induced growth arrest in lung cancer cell lines through anaphase catastrophe." (PMID 25301183, 2014).
ovarian carcinoma (80 papers, 2005 to 2025). A malignant neoplasm originating from the surface ovarian epithelium. "CDK-2 and cyclin E are fundamentally linked with some specific cancer types, including glioma and ovarian cancer, among others." (PMID 38184514, 2024). "Similarly, reduction of levels of the ribosomal protein RPS6 in ovarian cancer cells caused downregulation of CDK2, CDK4, CDK6, cyclin E, and cyclin D1, thereby blocking the transition from G0/G1 to S phase and suppressing cell proliferation." (PMID 38802745, 2024). "Nevertheless, in ovary cancer, it is known that the increase in the percentage of cells in G1 in response to melatonin (range from 0 to 800 μM) is associated with a downregulation of cyclin-dependent kinases 2 and 4 (CDK2 and CDK4)." (PMID 30386380, 2018). "In ovarian cancer cells, we also reported that mifepristone promoted the upregulation of p21cip1 and p27kip1 and their association with Cdk2 in the nuclear compartment, thus blunting the activity of Cdk2 otherwise required to drive G1/S cell cycle progression." (PMID 25252652, 2015). "For instance, the overexpression of CCNE1 in ovarian cancer has been shown to promote genomic instability through its interaction with CDK2, which accelerates the cell cycle and impairs DNA repair mechanisms." (PMID 39591374, 2024). "It was also observed to significantly reduce the expressions of cyclin D1 and cyclin E, together with CDK4 and CDK2 in the ovarian cancer cells (anti-ovarian)." (PMID 39364049, 2024). "HGSOC cells exhibiting CCNE1 amplification display elevated CDK2 expression, and reducing or inhibiting CDK2 leads to decreased ovarian cancer cell proliferation." (PMID 38255960, 2024). "Aberrations in the cyclin D1/E1–cyclin-dependent kinase (CDK2/4/6)–retinoblastoma (RB) pathway can promote an aggressive ovarian cancer phenotype." (PMID 38612869, 2024). "In the current study, we evaluated the prognostic and predictive significance of the CDK2/4/6–cyclin D1/E1–pRB1 axis in clinical ovarian cancers (OC)." (PMID 38612869, 2024). "To test if a CDK2 inhibitor in combination with etoposide is anti-tumorigenic in vivo, we used the OVCAR-3 xenograft, a model previously used to validate CDK2 as an oncogenic driver in CCNE1-amplified ovarian cancer." (PMID 37519629, 2023). "We showed that CDK1 and CDK2 regulate MLK3 to control JNK activity during cell cycle progression in human ovarian cancer cells." (PMID 35843311, 2022). "The results of the western blot assay indicated that trichodermin significantly suppressed the expression of cyclin D1, CDK4, CDK2, p-Rb, and Rb in both ovarian cancer cell lines." (PMID 34065149, 2021). "shBTG2 caused a notable increase in the expression of the cell cycle proteins Cyclin D1 and CDK4, while GV-BTG2 decreased Cyclin D1, CDK4 and CDK2 expression in ovarian cancer cells." (PMID 34485119, 2021). "Knockdown of the CCNE1 and CDK2 genes in known CCNE1 amplified ovarian cancer cell lines has led to reduced clonogenic survival, but this has not been seen with the CDK2 inhibitor daniciclib when given as monotherapy." (PMID 34485660, 2021). "The results revealed that 3′ UTR luciferase reporter activity of CDK2 and CyclinD1 was upregulated in Cul4B overexpressing ovarian cancer cells." (PMID 32622365, 2020). "Cul4B regulates the expression of CDK2 and CyclinD1 by repressing miR-372.These results indicate a role of Cul4B in the regulation of cell cycle in ovarian cancer." (PMID 32622365, 2020). "Here, we observed that cyclin H was positively correlated with the increased tumor grade of ovarian cancer and the expression of the proliferation markers Ki-67 and p-CDK2." (PMID 32694938, 2020). "The same in ovarian cancer cells where the inhibition of Shp1 activity reduces tumor growth by increasing intracellular levels of the Cdk2/p27(kip1) and Cdk2/Shp1 complexes." (PMID 32596156, 2020).
ovarian carcinoma (continued). "The signaling molecules perturbed by CCRK are divergent and cancer-specific, including the cell cycle regulators CDK2, cyclin D1, cyclin E and RB in glioblastoma, ovarian carcinoma and colorectal cancer and lung cancer." (PMID 30846786, 2019). "We previously reported that ISL induced G2/M arrest by up-regulation of CDK2 protein expression and down-regulation of cyclin B1 protein expression in ovarian cancer." (PMID 31394829, 2019). "Deregulation of the CDK2/4/6 signaling pathway is among the most common aberrations found in ovarian cancer." (PMID 30108608, 2018). "Our previously published results concerning the action of leptin receptor antagonists on epithelial ovarian cancer cells showed that both antagonists studied decreased cdk2 and cdk4 protein expression in CaOV-3 and OVCAR-3 cells." (PMID 28861689, 2017). "Inhibition of CDK2 in ovarian cancer cells overexpressing cyclin E has also been shown to significantly suppress cancer cell proliferation." (PMID 27285764, 2016). "This suggests that the majority of ovarian cancer cell lines are cyclin E1/CDK2-dependent, confirming earlier reports." (PMID 25557169, 2015). "The results demonstrated that following transfection of the WWOX gene, ovarian cancer stem cells expressed significantly lower levels of cyclin E, CDK2, cyclin D1 and CDK4 proteins than the empty plasmid group and the control group." (PMID 25891642, 2015). "This possibility is supported by our observation that Cdk2 inhibitor SNS-032 suppressed metastatic colonization of CCNE1-overexpressing ovarian cancer cells and greatly prolonged the survival of mice bearing ovary tumors with CCNE1 overexpression." (PMID 26204491, 2015). "Previous studies have shown that MF induces G1-S blockage of the cell cycle through inhibition of cdk2 activity in human ovarian cancer cells." (PMID 25622528, 2015). "Previous studies have shown that Mifepristone induces G1-S blockage of the cell cycle through inhibition of cdk2 activity in human ovarian cancer cells." (PMID 23530939, 2013). "High-levels of CCNE1 protein, an activating subunit of the cyclin dependent kinase 2 (CDK2), are often observed in patients with ovarian cancer." (PMID 22355333, 2012). "Our previous studies in ovarian cancer cells indicated that MF-induced growth inhibition occurs through G1 cell cycle arrest and a profound inhibition of the G1/S kinase, Cdk2." (PMID 21619605, 2011). "In the discovery set, SNPs in several genes were found to be associated with the risk of ovarian cancer; of these, five genes (ABL1, CCND3, CDKN1A, E2F3 and CDK2) were significant in log-additive models (P-value <0.05)." (PMID 19738611, 2009). "In vitro, BMS-387032 inhibits Cdk2 phosphorylation in the A2780 ovarian carcinoma cell line, inhibiting the phosphorylation of downstream targets of Cdk2 including pRb, histone H1 and DNA polymerase-α." (PMID 15558073, 2005). "CDK2 targeting in cyclin-E1-overexpressing ovarian cancer will have a positive clinical impact." (PMID 38612869, 2024). "Prior research has revealed that HGSOC cells with CCNE1 amplification display elevated CDK2 expression, and reducing or inhibiting CDK2 could lead to decreased ovarian cancer cell proliferation." (PMID 38255960, 2024). "CDK2/4/6 inhibitors are emerging targets in ovarian cancer therapeutics." (PMID 38612869, 2024). "High nuclear CDK2 was seen in 28% and high cytoplasmic CDK2 was observed in 28% of ovarian cancer." (PMID 38612869, 2024). "Additionally, in ovarian carcinoma, reduced EZH2 phosphorylation caused by CDK2 inhibition was found to activate downstream ESR1." (PMID 35846880, 2022). "Moreover, the evaluation of the miR-124 overexpression in MSC exosomes has shown the proliferation inhibition of ovarian cancer cells by arrest induction in the S phase through the downregulation of Cyclin-Dependent Kinase 2 (CDK2), CDK4, and CDK6." (PMID 34307654, 2021).